CDK4 (cyclin dependent kinase 4)
Diseases named in the same sentence as CDK4 in open-access papers (continued):
Sharing a sentence is not in itself a finding about the gene and the disease.
tumor (continued). "GLI1 overexpression significantly accelerates tumor growth and upregulated p-AKT, CDK4, and cyclinD3 in vivo." (PMID 33658491, 2021). "In preclinical models, CDK4/6 inhibitors overcome BRAF/MEK inhibitor resistance, leading to sustained tumour regression; however, the metabolic response to this combination has not been explored." (PMID 33572972, 2021). "Further study indicated that the anti-tumor activity of MRTX849 was significantly improved when combined with upstream (EGFR and SHP2) inhibitors and downstream (mTOR and cyclin-dependent kinase 4/6) (CDK4/6) inhibitors." (PMID 34742312, 2021). "•An increase in tumor purity was positively correlated with the expression of CDK-1 in COAD due to CD4+ cells and CDK-4 in COAD and READ resulting from a fraction of immune cells." (PMID 33732631, 2021). "A subsequent mitotic error results in the loss of one copy of chromosome 18 in multiple EC cells, which would decrease MIR1 expression, increase CDK4 expression, and attenuate the RB1 tumor suppressor pathway." (PMID 34680217, 2021). "SHR6390, a novel CDK4/CDK6 inhibitor, demonstrates high potency in in vitro antiproliferative action toward the spread of Rb-positive human tumor cells." (PMID 34361615, 2021). "propose that CDK4 regulates prometastatic inflammatory cytokine signaling, whereas CDK6 mainly controls DNA replication and repair processes, indicating that CDK4 and CDK6 facilitate tumor growth and progression in multiple cancers." (PMID 35095879, 2021). "Although the overexpression of CDK4 and cyclin D1 is also observed in EMPD tumor cells, the correlation between their expression and patients’ prognosis has not been elucidated." (PMID 34395284, 2021). "Immunohistochemistry staining of the tumor tissues showed significantly reduced expressions of Rb, CDK2, CDK4, and CDK6 in vanoxerinedihydrochloride treatment group, as compared to control PBS treatment group." (PMID 33579185, 2021). "Coadministration of CDK4 and MEK inhibitors in heterogeneous tumors effectively targeted different tumor subpopulations, subverting the resistance to either single-agent treatment." (PMID 34309585, 2021). "Decreased the protein expression of CDK2, CDK4, cyclin E, and Bcl-2 and increased the expression of CDKN1BElevated the ratio of LC3-II/LC3-I.Decreased tumor size and weight." (PMID 34026649, 2021). "CDk4/6 can bind to cyclin D, which enables cells to enter S-phase through the RB-EF2 pathway and promotes tumor cell proliferation." (PMID 33859752, 2021). "mRNA expression levels of CDK4 and CDK6 were overexpressed in CCA tumor samples when compared to normal samples." (PMID 33116269, 2020). "Roniciclib binds to and inhibits the activity of CDK1/Cyclin B, CDK2/Cyclin E, CDK4/Cyclin D1, CDK6/Cyclin D3, and CDK9/Cyclin T1, which are serine/threonine kinases playing key roles in the regulation of tumor cell proliferation and survival." (PMID 32737364, 2020). "CDK6 is an upstream regulatory element of nuclear factor of activated T cells (NFAT), and CDK4/6 inhibitors suppress NFAT phosphorylation, the activation of CTLs, and its ability to kill tumor cells." (PMID 32357912, 2020). "High phosphorylation of Rb by activating Cyclin D-CDK4 /CDK6 complex was an important reason for the rapid proliferation in GBM cells and the proliferation capacity of tumor cells was significantly reduced after the intervention of CDK4/CDK6 inhibitors." (PMID 32860670, 2020). "Agents have been developed to directly reactivate tumour suppressors or target-related molecules, such as MDM2, CDK4/6 and TGF-β." (PMID 33008426, 2020).
tumor (continued). "While previous studies have shown MEK, CDK4/6 and WEE1 as promising kinase targets for inhibiting tumor growth, druggable kinases against RMS self-renewal have been poorly characterized." (PMID 32363002, 2020). "Other studies showed that CDK4 and CDK6 played a role in anti-apoptosis via inhibiting the activation of Caspase 3 in tumor cells." (PMID 32860670, 2020). "The immunohistochemical analyses performed on the tumor of the first case were positive for MDM2 and CDK4." (PMID 31282548, 2020). "In our series, the immunohistochemical analyses performed on the first case of atypical lipomatous tumor stained positive for MDM2 and CDK4." (PMID 31282548, 2020). "In mammary fat pad xenografts, both CDK4/6 and TROJAN inhibition exhibited significant tumor growth reduction, whereas the combination of CDK4/6 and TROJAN inhibition further reduced tumor growth." (PMID 32393270, 2020). "CDKN1A is a tumor suppressor that mainly functions as a cell cycle checkpoint by binding to CDK1, Cyclin‐dependent kinase 2 (CDK2), or the CDK4/6 complex." (PMID 33037696, 2020). "In accordance with these findings, the tumor cells from the knockout mice had a higher expression of the proliferation markers PCNA, Cyclin D1 and CDK4." (PMID 33245729, 2020). "Among these cell lines, HT29 cell line was highly expressed with FBX8, SOX-2 and SOX-2, and CD44, while quite weakly expressed with CDK4, HIF-1α, and c-Myc, indicating that HT29 cell line was an appropriate model to study tumor dormancy." (PMID 32796813, 2020). "Some other cyclin family members, such as cyclin-dependent kinase 4 or cyclin D1 (CCND1), also mediated pathological process in tumor cells and motivated cellular metastasis and tumor invasiveness." (PMID 33628185, 2020). "We found that BACE2 knockdown led to significantly decreased levels of p‐p65 and key tumour promoters, namely CDK2, CDK4, cyclin D1 and c‐Myc." (PMID 31856384, 2020). "A systematic study of enzymatic and cellular assays led to the identification of compound X22 with a nanomolar potency against CDK4 and CDK9 and potent antiproliferative activities against a panel of tumour cell lines." (PMID 31899991, 2020). "In summary, we have shown that GAS7, a direct downstream target of miR-362-5p, can exert its tumor suppressive functions in THP-1 cells through regulation of PCNA, CDK4, cyclin D1, and p21." (PMID 31925702, 2020). "Consistent with the in vitro results, THP-1 tumor cells exhibited high expression of GAS7 protein and low expression of CDK4 after treatment with miR-362-5p inhibitor, which was notably reversed after treatment with miR-362-5p mimic." (PMID 31925702, 2020). "Several compounds inhibited CDK4 and CDK9 at low nanomolar levels and exhibited good antiproliferative activities in a panel of tumour cells." (PMID 31899991, 2020). "This combination inhibits RB hyperphosphorylation by inhibiting the cyclin D1/CDK4/CDK6 complex, inducing cell cycle arrest and inhibiting tumor growth." (PMID 32508030, 2020). "SRX3177 displayed greater tumor cytotoxicity as compared to the dual BRD4/PI3K inhibitor, SF2523 or dual BRD4/CDK4/6 inhibitor, SRX3177P." (PMID 32793389, 2020). "Western blotting results indicated that the protein level of BRD4, c-Myc, CyclinD1, CDK4, MMP-2, MMP-9, Vimentin and N-cadherin were all decreased while E-cadherin was increased in the tumor with circCELSR1 knockdown." (PMID 32640974, 2020). "FBX8 not only maintains the stemness of tumor cells but also regulates the biological functions of dormant tumor cells by targeting HIF-1α, CDK4, and C-Myc." (PMID 32796813, 2020).
tumor (continued). "Concurrent inhibition of IGF1R and CDK4/6 has shown a greater decrease in cell viability than achieved by a single drug in both NCI-H295R and MUC1 cells, as reported in different tumor cell lines." (PMID 32373071, 2020). "Molecular profiling analysis of the human tumor sample from which the PDX was derived revealed CCND1 amplification, suggesting its potential sensitivity to CDK4/6 inhibitors." (PMID 33116269, 2020). "The CDK4 and CDK6 overexpression and copy number gain in CCA tumor samples further suggest potential sensitivity of CCA to palbociclib treatment." (PMID 33116269, 2020). "Amplifications of EGFR and gain of chromosomes 19 and 20 were strongly prevalent in RTK II, and PDGFRA, CDK4 and MDM2 or MDM4 amplifications were more frequent in RTK I tumours." (PMID 33339831, 2020). "Consistently, we observed decreased cyclin D1 and CDK4 levels and delayed cell growth in UCHL5 knocked down tumor cells." (PMID 33046988, 2020). "MYC acts as a transcriptional factor that regulates the transcription of over 15% of human genes, such as CCND, CDK4 and E2F1, which are involved in tumour progression." (PMID 31907353, 2020). "Finally, the observation that adding CDK4/6 inhibitors to NET might stimulate anti-tumor immunity, as has been observed with some chemotherapy agents, suggests that patients with ER+ LABC could see improved benefit from second-line immunotherapy approaches, while avoiding cytotoxic chemotherapies." (PMID 32690069, 2020). "The GEP and CNA pattern for the EGFR, CDK4, MDM4, and PDGFRA genes was available in 83/83, 68/83, 68/83, and 68/83 GBM tumor samples evaluated, respectively." (PMID 31963499, 2020). "We analyzed CDK4, CDK6, cyclin A, cyclin D1, ATF4, and CHOP protein levels in excised tumor sections from saline- and CPX-treated groups." (PMID 32719342, 2020). "To enhance the anti-tumor effect of sorafenib, we employed PD0332991 (CDK4/6-Rb inhibitor) based on the correlation between SIRT3 and phosphorylated retinoblastoma protein in HCC." (PMID 32306906, 2020). "In agreement with promoting tumor cell vitality, PDLIM7 was shown to stabilizes MDM2 by interfering with its autoubiquitination resulting in reduced responsiveness toward CDK4/6-inhibition by PD03329921 in cancer cells." (PMID 30371874, 2019). "Western blot data showed that the protein levels of PCNA, CDK4, CDK6, Cyclin D1, MMP-2, MMP-9, and Bcl-2 were decreased, but cleaved caspase-3 was increased in tumor tissues of ApoE KO mice compared to those of WT mice." (PMID 31275318, 2019). "MYC, a master regulator of transcription, activates Ras/ERK proliferative pathways while CDK4 and CCDN1 contribute to tumor advancement by promoting of G1 phase of cell cycle in CRC." (PMID 31409279, 2019). "Interestingly, CDK4/6 inhibitors might display influences on the tumor microenvironment." (PMID 31777590, 2019). "Decreased CDK2 activity and the increased presence of p21CIP1 in anti-CDK2 precipitates were consistently observed in multiple tumour cell lines subject to combined MET and CDK4 inhibition." (PMID 31296956, 2019). "Teo and colleagues showed that a combination of CDK4/6 and PD1 blockade resulted in a synergistic inhibition of tumor growth." (PMID 30959874, 2019). "The PI3K/AKT pathway is closely related to the proliferation, differentiation, apoptosis, migration, and adhesion of tumor cells involving multiple targets, including EGFR, BCL2, GSK3B, CDK2, and CDK4." (PMID 31406500, 2019). "This provides a strong rationale for the combined targeting of both the CDK4/6 and PI3K pathways in effective control of the tumor progression." (PMID 31178825, 2019). "Cell cycling proteins CDK4 and cyclin B1 were also reduced, as were markers for epithelial–mesenchymal transition (EMT) and fibronectin in both tumor types but vimentin was reduced in tumors induced by B16-F10." (PMID 31615091, 2019).
tumor (continued). "In breast cancer cells, inhibition of CDK4/6 enhanced tumor antigen presentation, suppressed the proliferation of regulatory T-cells (T-reg), and promoted CD8 T-cell mediated tumor regression." (PMID 31817861, 2019). "There is crosstalk between the CDK4/6 and the PI3K–mTOR pathways, resulting in a good rationale for testing the combined inhibition of the two pathways in order to block tumor growth." (PMID 30959874, 2019). "The objective of this study was to evaluate the anti-tumor activity of elacestrant, a novel oral selective estrogen receptor degrader (SERD), in preclinical models of CDK4/6i resistance." (PMID 31852484, 2019). "Second, inhibition of CDK4/6 decreases the repression of NFAT family proteins and their target genes, critical regulators of T cell function, which in turn increases tumor infiltration and activity of effector T cells." (PMID 30863749, 2019). "Reduced expression of SIRT2 upregulated cyclin-dependent kinase 4 (CDK4) expression, which eventually accelerated cell proliferation, migration, and invasion, indicating that SIRT2 plays a tumor-suppressor role in OC." (PMID 31572453, 2019). "Whereas we found pronounced tumor angiogenesis in control tumors, de novo blood vessel formation when analysed by CD31 staining was strongly reduced in the CDK4 and CDK6 knockdown residual tumors." (PMID 30858922, 2019). "shRNA knockdown of either CDK4 or CDK6 significantly reduces cell proliferation and impedes their migratory capacity in vitro, which translates into a strong inhibition of tumor growth in xenotransplantation experiments." (PMID 30858922, 2019). "To corroborate the role of CDK4 in the inhibition of tumour growth by RN181, we reconstituted the expression of CDK4 in RN181‐overexpressing GC cells." (PMID 30714150, 2019). "CDK family members, such as CDK2, CDK4, and CDK6, play a key role in the cell-cycle control of tumor cells." (PMID 29370087, 2018). "Inhibition of CDK4 and CDK6 acts to restore the tumour suppressor role of Rb and promote cell cycle arrest." (PMID 30293995, 2018). "CDKN2A is an inhibitor of cyclin-dependent kinase 4 (CDK4) and CDK6, and it functions as a tumor suppressor." (PMID 30034186, 2018). "A decrease by 90% in the cyclin D1, CDK4 and CDK6 levels was observed in the erufosine treated tumor samples." (PMID 29464035, 2018). "Because the target of activated CDK4/6 is Rb, pRb levels were examined by immunohistochemistry (IHC) in ESR1 fusion-expressing T47D xenograft tumor sections." (PMID 30089255, 2018). "Western blotting of the xenograft tumour tissues from the nude mouse model showed that overexpression of ABHD11‐AS1 increased the expression of cyclin D1, CDK1, CDK2, CDK4, Bcl‐xl and VEGFA and decreased the expression of p16." (PMID 29799152, 2018). "Western-blot analyses of the tumor tissue lysates from 2HF treated mice revealed reduction in cell growth promoting signals such as AKT and p70S6K, proliferation signals such as CDK4 and cyclin B1." (PMID 30546837, 2018). "A mass of studies have demonstrated that PPARγ agonists via inhibiting the expression of cyclinD1, cyclinB, cyclinE, CDK4 and CDK2 and increasing the expression of CDKN1A to prevent cell cycle from G1 to S phase to prohibit tumor cells proliferation." (PMID 29642873, 2018). "CDK4 was identified as a key mediator of this proliferation, such that combined CDK4 and MEK inhibition led to tumor regression similar to that achieved by NRAS extinction." (PMID 30167080, 2018). "The expression levels of CDK4, CDKN2A, p14-ARF, and p16-INK4A, a tumor suppressor of NB, were decreased in CFC1-overexpressing cells." (PMID 28620148, 2017).
tumor (continued). "CNVs in tumour cells also enhance proliferation, albeit at the expense of the host; for example, copy number amplification can drive tumour growth (e.g., of FGFR2 or CDK4) or mediate drug resistance (e.g., of DHFR, KRAS or BRAF)." (PMID 28654659, 2017). "Currently, multiple CDK4/6 inhibitors are in phase III clinical trials and cyclin D-overexpressing tumours have been suggested to be a potential selective biomarker." (PMID 28177473, 2017). "Combined CDK4/6-PI3K inhibition overcomes intrinsic and adaptive resistance leading to tumor regressions in PIK3CA mutant breast cancer PDXs." (PMID 28499452, 2017). "The high DE tumor suppressor miRNA-449-A inhibits proliferation and prevents metastasis, and regulates the co-expressed GAS1 (putative tumor suppressor) and CDK4." (PMID 28824643, 2017). "For example, the combination of trametinib and CDK4/6 (cyclin dependent kinase 4/6) inhibitor was shown to be highly efficacious in inhibiting the growth of KRAS-mutant CRC cells and inducing the tumor regression in patient-derived xenograft models of CRC." (PMID 28756770, 2017). "Tumor cells displayed overexpression of MDM2, CDK4, and P16 by immunohistochemistry and CGH revealed amplification of 12q13-15 as the only genetic imbalance." (PMID 28377828, 2017). "Here, we aimed to evaluate the anti-tumor activity of SHR6390, which is an orally bioavailable, small molecule CDK4/6 inhibitor, in ESCC in vitro cell lines and in vivo PDXs models." (PMID 28578693, 2017). "p15 and p16 inhibits CDK4 and CDK6, therefore p15 and p16 act as tumor suppressors and lead to cell cycle arrest in the late G1 phase." (PMID 28484518, 2017). "In this context, the inhibition of CDK4/6 resensitized acquired-resistant xenograft mice models to HER2-targeted therapies and suppressed tumor recurrence in vivo." (PMID 28438180, 2017). "Preclinical studies have shown that targeting both the CDK4/6 and the PI3K signaling pathways results in tumor regression and reversal of PI3K inhibitor resistance in a MCF7 xenograft model." (PMID 28418845, 2017). "Recently, the combination of CDK4/6 and EGFR inhibitors has been shown to be effective in blocking tumor resistance in mice." (PMID 28513565, 2017). "In summary, our study focused on the mechanism of miR-486-5p as a tumor suppressor in NSCLC, and our findings revealed that it functioned, in part, through targeting CDK4, an important component of the CDK4/6 signaling pathway." (PMID 27049724, 2016). "IHC staining demonstrated that upregulation of Tspan5 significantly increased the expression of p27 and p15 but dramatically decreased the expression of cyclin D1, CDK4, pRB and E2F1 in xenograft tumours compared to control tumours (all P<0.001)." (PMID 27223087, 2016). "As a consequence, it is concluded that C3G activity on tumor growth inhibition was probably through KLF6-mediated p21 induction, by disruption of the Cyclin D1 and CDK4 interaction, thus blocking the cell cycle." (PMID 27690088, 2016). "More importantly, either upregulation of p15 and p27 or downregulation of cyclin D1, CDK4, pRB and E2F1 in tumour cells were also found in xenografted tumours of GC." (PMID 27223087, 2016). "An important anti-tumor mechanism of hSulf-1 operates by decreasing downstream AKT signaling pathway activity and inhibiting the nuclear import of CDK4." (PMID 27806323, 2016). "The correlation of Tspan5 expression with the expression of p27, p15, cyclin D1, CDK4, pRB and E2F1 in vivo are also revealed in xenografted tumours." (PMID 27223087, 2016). "In this study, we explored the therapeutic effects of CDK4/6 inhibition, using the novel small-molecule CDK4/6 inhibitor, LY2835219 in both cell lines and tumor xenograft models of HNSCC." (PMID 26909611, 2016).